INS (insulin)
Diseases named in the same sentence as INS in open-access papers (continued):
Sharing a sentence is not in itself a finding about the gene and the disease.
Insulin resistance (continued). "The pathogenesis of gestational diabetes mellitus is intricate, dominated by insulin resistance and insufficient insulin secretion." (PMID 39416628, 2024). "One mechanism by which insulin resistance leads to atherosclerosis and cardiovascular disease is via vascular stiffness, and defective insulin signaling in atherosclerotic lesion cells also links insulin resistance and atherosclerotic vascular disease." (PMID 38812015, 2024). "These inflammatory mediators disrupt insulin signaling pathways, resulting in insulin resistance and hyperglycemia." (PMID 38694942, 2024). "The lowering effects of PHTG, insulin, and insulin resistance tended to be greater as the exercise intensity increased." (PMID 38021207, 2024). "Higher concentrations of TG increase free fatty acids, decrease insulin sensitivity, and contribute to insulin resistance." (PMID 38628590, 2024). "Based on cut-off values for insulin resistance (defined as HOMA-IR ≥2.1) all but one of the included studies had a insulin resistant intervention or control group at baseline." (PMID 39276209, 2024). "Clinically, high blood levels of insulin in insulin resistance activates SREBP-1 that leads to hepatic steatosis." (PMID 38675168, 2024). "When insulin resistance is low, the pancreatic beta cells can still satisfy the body’s insulin requirement, leading to nearly normal HOMA-β levels." (PMID 39876919, 2024). "A study involving Chinese adults found that non-diabetic subjects with the AA genotype had significantly higher fasting insulin levels and homeostasis model assessment-estimated insulin resistance (HOMA-IR) indices, indicating reduced insulin sensitivity." (PMID 39766897, 2024). "Significant improvements in glucose, insulin, and insulin resistance were observed earlier in subjects with the AA genotype compared to AG and GG genotypes." (PMID 39125390, 2024). "This escalation likely stems from heightened insulin secretion in response to carbohydrates among individuals with insulin-resistance and obesity." (PMID 39027659, 2024). "Impaired mitochondrial β-oxidation of fatty acids can lead to increased accumulation of lipid intermediates, such as diacylglycerol (DAG) and ceramides, which can impair insulin signaling pathways and contribute to insulin resistance." (PMID 38920999, 2024). "MI as a molecule with insulin‐mimetic features improved insulin resistance (IR) in terms of all IR‐related indices, apart from quantitative insulin sensitivity check index." (PMID 39479697, 2024). "STZ selectively destroys insulin-producing beta cells in the pancreas, while NIC partially protects against STZ's cytotoxic effects, resulting in an animal model that mimics the insulin resistance and partial insulin deficiency seen in human T2DM." (PMID 39350820, 2024). "After excluding age and years of infertility as potential confounders, patients with PCOS demonstrated significantly higher body weight and insulin levels, exhibiting characteristics of obesity and insulin resistance, consistent with previous research." (PMID 38600539, 2024). "Our study investigated insulin signaling in insulin resistance using a liver cell model undergoing an insulin resistance-inducing protocol." (PMID 39572596, 2024). "Training interventions, ranging from few days to several months, in healthy subjects and insulin-resistant subjects (at various insulin resistance degree) provided more direct evidence of physical training-induced benefit on insulin sensitivity." (PMID 39595594, 2024). "Progranulin concentrations were positively correlated with body mass index (BMI), fat mass, fasting glucose and insulin levels, as well as insulin resistance." (PMID 38339094, 2024). "In detail, estrogens activate the estrogen receptor α (ERɑ) pathway, which protects against insulin resistance and retains mitochondrial function in insulin-sensitive tissues." (PMID 39045408, 2024).
Insulin resistance (continued). "The early stage of T2DM is usually characterized by insulin resistance, in which the body’s sensitivity to insulin decreases, resulting in increased blood glucose levels after meals." (PMID 39737156, 2024). "After treatment with BPE and polyphenol compounds (B, D, G groups), serum insulin levels were significantly reduced, resulting in a substantial alleviation of the insulin resistance state, approaching the levels observed in the Met group." (PMID 39765819, 2024). "Preclinical results have shown promising results, with 83% of the studies that examined glucose tolerance possibly due to a direct impact of PBM on islet insulin secretion capability and insulin resistance reporting an improvement in these parameters." (PMID 38567306, 2024). "Participants with MetS exhibited significantly higher values of WC, BP, fasting glucose, TG, fasting insulin, and insulin resistance, along with lower levels of HDL-C (all p< 0.001) compared to non-cases." (PMID 39106225, 2024). "HOMA analysis takes into account both serum insulin and fasting blood glucose and has been validated as a measure of insulin resistance and beta cell function." (PMID 39683552, 2024). "The biological processes through which T2D develops are diverse and include impaired insulin secretion and insulin resistance." (PMID 38374256, 2024). "This systematic review and meta-analysis sought to investigate the influence of psyllium on HbA1c, fasting blood sugar (FBS), insulin, and Homeostatic Model Assessment of Insulin Resistance (HOMA IR), owing to the equivocal results in the extant literature." (PMID 38844885, 2024). "In the context of the natural menstrual cycle, small but significant changes in insulin and insulin resistance index (HOMA-IR) correspond in part to the levels of estradiol and progesterone." (PMID 38348417, 2024). "Type 2 diabetes is characterized by insufficient insulin secretion and insulin resistance, which is the reduced sensitivity of target organs to insulin action." (PMID 38884020, 2024). "The relationship between the treatment response and the level of insulin resistance supports the involvement of insulin in the pathophysiology of MDD." (PMID 38398483, 2024). "Molecularly, glucose intolerance can be explained in part by insulin resistance and perturbed insulin signaling in both the skeletal muscle and hepatic tissues." (PMID 38393018, 2024). "Resistin was positively associated with insulin levels in CRC, whereas blockade of resistin by antibodies resulted in a decrease in blood glucose levels and insulin resistance." (PMID 39184804, 2024). "Insulin plays a central role in the regulation of energy and glucose homeostasis, and insulin resistance (IR) is widely considered as the “common soil” of a cluster of cardiometabolic disorders." (PMID 38332892, 2024). "Insulin resistance (IR), metabolic syndrome (MS), and decreased insulin production are hallmarks of T2DM; these factors contribute to the pathophysiology of the disease and make it practically impossible to effectively manage glycemic levels." (PMID 39063997, 2024). "Type 2 DM is a chronic metabolic condition characterized by insulin resistance where the body is unable to effectively use insulin, leading to high blood glucose levels or hyperglycemia." (PMID 38339160, 2024). "Total SR PC levels, but not total SR PE levels or PC:PE ratio, were significantly negatively correlated with BMI, waist circumference, total fat, visceral adipose tissue, triglycerides, fasting insulin, and homeostatic model assessment for insulin resistance." (PMID 38354857, 2024). "Currently, due to the benefit of adding long-acting insulin analog, it is an accepted practice in our institution to add glargine along with the intravenous insulin infusion to patients with insulin resistance and severe lactic acidosis." (PMID 38365663, 2024).
Insulin resistance (continued). "Taken together, these findings underscore the significance of mitochondrial dysfunction induced by efavirenz in the development of insulin resistance in insulin-sensitive tissues." (PMID 39288128, 2024). "In this study, we found consistent associations between the VDR-BsmI polymorphism and HOMA-IR, insulin-to-glucose ratio and FIRI insulin resistance index." (PMID 38233797, 2024). "Insulin resistance refers to the decreased responsiveness of tissues that target insulin, even at elevated physiological levels of the hormone." (PMID 39610878, 2024). "Insulin resistance (IR) is a prominent feature of metabolic syndrome, referring to a decrease in the efficiency of insulin in promoting glucose utilization." (PMID 38419039, 2024). "Insulin resistance is a condition in which the resulting metabolic action of insulin in the target tissues is inadequate for a given quantity of insulin." (PMID 39061991, 2024). "While this likely depends on several mechanisms, data from both in vitro and clinical trials suggest that impaired insulin sensitivity in white adipose tissue plays an early role in dysregulation of adipocyte metabolism and whole-body insulin resistance." (PMID 38579770, 2024). "Recently, the elucidation of the involvement of both estrogen and progesterone in heightened insulin resistance in women has shed light on the intricate interplay between sex hormones and insulin." (PMID 40302954, 2024). "Although insulin resistance is more commonly diagnosed in women, some studies, in fact, suggest that men have lower peripheral insulin sensitivity than women." (PMID 38792339, 2024). "Surrogate measures of insulin resistance have been evaluated in AAb+ relatives with varying conclusions, possibly because of the confounding effect of abnormal insulin secretion." (PMID 37914981, 2024). "Our primary outcome measures include fasting plasma glucose, fasting serum insulin, and insulin resistance utilizing homeostatic model assessment for insulin resistance (HOMA-IR)." (PMID 39345888, 2024). "Animal studies have shown that in mice exposed to PFAS, PFAS negatively regulates the protein kinase B (PKB) pathway in white adipose tissue, resulting in increased glucose and decreased insulin and insulin resistance." (PMID 38633237, 2024). "In obese ob/ob mice, FXR deficiency was protective against weight gain and peripheral insulin resistance, as shown by improved glucose clearance and adipose tissue insulin sensitivity." (PMID 38180064, 2024). "During insulin resistance, the reduced sensitivity of target tissues to insulin, the disrupted mitochondrial function, and the accumulation of BCAA suggest a potential relationship between the variables." (PMID 38999929, 2024). "Insulin resistance (IR) is characterized by the diminished responsiveness of cells to the glucose-lowering effects of both exogenous and endogenous insulin compared to the normal population." (PMID 38539404, 2024). "The cytokines have a detrimental impact, as they induce insulin resistance by inhibiting insulin signal transduction." (PMID 39275164, 2024). "Cyp2e1−/− mice are protected from high-fat-induced insulin resistance with insulin, which is known to decrease Cyp2E1 expression." (PMID 40452921, 2024). "Activated immune cells release cytokines such as TNFα and IL-1β, which activate a series of intracellular signalling pathways, altering insulin signalling and inducing insulin resistance." (PMID 38999869, 2024). "Individuals with insulin resistance are those who, at a given plasma insulin concentration, are unable to uptake and metabolise as much glucose as they should." (PMID 38542702, 2024). "QUICKI and the triglyceride: HDL ratio are two other important measures to assess insulin sensitivity and insulin resistance." (PMID 39421410, 2024).
Insulin resistance (continued). "Shunting of portal-hypertensive-associated insulin from the portal venous system into the systemic circulation causes hyperinsulinemia, insulin receptor desensitization and insulin downregulation, leading to insulin resistance." (PMID 39040676, 2024). "Our results showed a significant decrease in choline levels with progression from insulin sensitivity to insulin resistance and T2D." (PMID 39195553, 2024). "TSH can directly reduce the synthesis and secretion of insulin in pancreatic β cells and can also affect insulin resistance." (PMID 38212787, 2024). "Insulin resistance occurs when tissues such as skeletal muscle, adipose tissue, and the liver become less responsive to insulin, leading to reduced glucose uptake, hyperglycemia, and hyperinsulinemia, and eventually, T2D." (PMID 39238503, 2024). "As the indicator of insulin resistance, the euglycemic hyperinsulinemic clamp method is the gold standard for evaluating tissue-specific insulin sensitivity." (PMID 39803116, 2024). "This can be understood by comparing the relationship between elevated plasma insulin levels and the insulin resistance that is observed in the state of obesity." (PMID 38474226, 2024). "In this study, phosphorylated IGFBP-1 correlated inversely with fasting insulin, and homeostatic model assessment-insulin resistance (HOMA-IR)." (PMID 39595651, 2024). "In chronic insulin stimulated-insulin resistance model, the basal and insulin-stimulated glucose uptake is more profoundly affected in insulin resistant 3T3-L1 cells compared to SGBS cells." (PMID 39749015, 2024). "Firstly, FGF21 reduces insulin resistance by stimulating insulin secretion via the PI3K/Akt signaling pathway, enhancing postprandial insulin sensitivity." (PMID 39687000, 2024). "The triglyceride glucose (TyG) index and triglyceride-to-high-density lipoprotein cholesterol (TG/HDL-C) ratio are widely recognized as simple non-insulin-based indices for assessing insulin resistance." (PMID 39465132, 2024). "In insulin resistance situations, the actions of insulin in the cardiovascular system are reduced, resulting in decreased production of NO and its vasodilating action, favoring high blood pressure." (PMID 38685068, 2024). "In the insulin resistance phase, higher-than-normal levels of insulin are required in order to maintain the normal function of this hormone." (PMID 39768947, 2024). "RBP4 contributes to the development of insulin resistance by impairing insulin signalling in skeletal muscle and adipose tissue, upregulating lipolysis and inflammation in adipose tissue and increasing gluconeogenesis and lipid accumulation in the liver." (PMID 39318364, 2024). "Glucose metabolism indicators, including fasting glucose, insulin levels, and the insulin resistance index HOMA-IR, worsened as BMI increased." (PMID 39796506, 2024). "Development of insulin resistance in these mouse strains is likely due to high levels of circulating insulin levels and consistent with previously reported results." (PMID 38307384, 2024). "Both impairments in insulin signaling and the dysfunction of β-cells can lead to insulin resistance, metabolic syndrome, and T2DM." (PMID 39795155, 2024). "Insulin resistance is a condition in which insulin is unable to exert its normal biological activity of facilitating the entry of glucose into insulin-sensitive tissues to be used as the primary energy substrate." (PMID 39337658, 2024). "Topiramate, promotes insulin secretion and enhances insulin sensitivity, offering an effective solution for the critical challenges of β-cell dysfunction and insulin resistance in T2DM." (PMID 38715799, 2024). "The dynamic interplay between insulin demand and secretion is crucial in maintaining normal glucose homeostasis, with insulin resistance and beta-cell function playing pivotal roles in the development of T2D in childhood and adolescence." (PMID 38550917, 2024).
Insulin resistance (continued). "Insulin resistance is defined as insulin desensitization, characterized by a decrease in the level and function of insulin signaling pathway elements." (PMID 39830652, 2024). "In comparison with Leflunomide and Methotrexate, HCQ has a favorable effect on decreasing insulin levels, thereby reducing insulin resistance." (PMID 39273629, 2024). "Type 2 diabetes (T2D) is characterized by increased peripheral insulin resistance and a relative insufficiency of insulin secretion so as to overcome the insulin resistance." (PMID 38977131, 2024). "These factors can disrupt insulin signaling pathways, further aggravating the condition of insulin resistance." (PMID 38449844, 2024). "As insulin resistance increases, theremay be a failure of pancreatic β-cells to adequately meet the demands for insulin secretion, resulting in elevated HOMA-β levels." (PMID 39876919, 2024). "Abdominal obesity contributes to insulin resistance and regular exercise helps to reduce body fat, thereby increasing cellular sensitivity to insulin." (PMID 38440349, 2024). "Coumarins such as scoparone possess insulin-sensitizing properties and have been investigated for their potential to alleviate insulin resistance." (PMID 39070783, 2024). "The excessive accumulation of lipid intermediates, such as diacylglycerols and ceramides, in tissues like skeletal muscle and liver can impair insulin signaling, leading to insulin resistance." (PMID 39595621, 2024). "Some of these have been shown to help women with PCOS improve insulin sensitivity and reduce insulin resistance." (PMID 38276279, 2024). "This serine phosphorylation of IRS-1 inhibits its ability to propagate the insulin signal effectively, leading to further impairment of glucose uptake and exacerbation of insulin resistance." (PMID 39519193, 2024). "C-peptide concentrations are seen to be a more valid indication of insulin resistance than insulin secretion." (PMID 38474713, 2024). "T2DM is the inability of the body’s cells to absorb and use insulin, leading to the accumulation of glucose in the blood, which is defined as insulin resistance." (PMID 39410536, 2024). "We used the OGTT to estimate insulin resistance and relying on glucose and insulin to estimate insulin resistance can be challenging." (PMID 38561248, 2024). "Insulin resistance is mostly found in the liver because of the basal insulin-dependent suppression of the hepatic glucose output in a fasting state." (PMID 39519551, 2024). "This reduction in nitric oxide (NO) availability is attributed to multiple factors, including a decrease in insulin-mediated NO synthesis and an increase in reactive oxygen species (ROS) generated during insulin resistance, which accelerates NO degradation." (PMID 39744210, 2024). "The immune-inflammatory mediators, such as TNF-α, IL-1, and IL-6, can lead to insulin resistance due to oxidative stress from high glucose intake, reduce insulin sensitivity, and produce high levels of these mediators in the bloodstream." (PMID 39199338, 2024). "The present study showed that AO and VGX impaired glucose tolerance with lower insulin secretion and higher insulin resistance, observed in the OGTT and ITT." (PMID 39063072, 2024). "Insulin resistance is defined as reduced tissue insulin sensitivity leading to a decreased responsiveness to insulin-mediated glucose disposal and compensatory hyperinsulinemia in an attempt to maintain euglycemia." (PMID 39682351, 2024). "Previous research has indicated that a high resistin level impairs glucose tolerance, increases insulin resistance in the liver, and impairs insulin activity." (PMID 39125415, 2024). "This is largely due to insulin resistance and the subsequent inability to produce enough insulin to compensate for the resistance." (PMID 38398503, 2024).